Y_RNA (Y RNA )
Gene: Miscellaneous RNA gene on chromosome 7 (73,039,085 to 73,039,186, forward strand). Ensembl gene ENSG00000273927.
Homologues: Orthologues: chimpanzee Y_RNA (99% identical), pig Y_RNA (75% identical). Paralogues in human: Y_RNA (100% identical), Y_RNA (97% identical), Y_RNA (93% identical), Y_RNA (92% identical), Y_RNA (90% identical), Y_RNA (89% identical), Y_RNA (87% identical), Y_RNA (85% identical), RNY3 (84% identical), RNY3P12 (84% identical), Y_RNA (84% identical), RNY3P1 (83% identical), and 98 more.